GLO1 (glyoxalase I)
Diseases named in the same sentence as GLO1 in open-access papers (continued):
Sharing a sentence is not in itself a finding about the gene and the disease.
breast carcinoma (continued). "lncRNA OIP5-AS1 promotes breast cancer progression by regulating miR-216a-5p/GLO1.CLIC2 is a useful biomarker for identifying breast cancer patients who could benefit from immune checkpoint blockade." (PMID 35224098, 2022). "Future clinical translation of cell permeable Glo1 inhibitors as adjunct chemotherapy may improve overall survival in breast cancer and other cancers with high Glo1 expression." (PMID 34790575, 2021). "Glo1-mediated MDR has a major role in poor survival outcomes in breast cancer which may be countered by clinical development of Glo1 inhibitors." (PMID 34790575, 2021). "On the other hand, an inhibition of Glo1 was observed in the irradiated breast cancer cells." (PMID 34208417, 2021). "High-throughput transcriptome profiling of GLO1-depleted breast cancer cells highlighted a pro-metastatic signature that establishes novel connections between MG dicarbonyl stress, extracellular matrix (ECM) remodeling by neoplastic cells and enhanced cell migration." (PMID 30674353, 2019). "DUSP5 overexpression decreases the migratory capacity of GLO1-depleted breast cancer cells." (PMID 30674353, 2019). "To understand how (hyper)activation of the MEK/ERK signaling cascade in GLO1-depleted breast cancer cells relates to their metastatic potential, we first considered that MEK/ERK signaling could be mediated by the physical translocation of ERK in the nucleus." (PMID 30674353, 2019). "This suggests weak inhibition of GLO1 activity may be sufficient to suppress breast cancer cells, particularly if used in combination with other targeted drugs, without damaging normal cells." (PMID 30559934, 2018). "For example, while GLO1 is overexpressed in breast carcinomas, colon adenocarcinomas, and head and neck squamous cell carcinomas, its expression level is lower in kidney clear cell carcinoma, kidney papillary cell carcinoma, and cholangiocarcinoma relative to the corresponding normal tissue." (PMID 29385725, 2018). "However, our study revealed that the frequency of Glo1 amplification is low (1.0%) in breast cancer and that alteration of Glo1 copy number, including gene amplification, did not correlate with poor clinical outcome." (PMID 30559934, 2018). "It thus appears that it is overexpression of GLO1 mRNA rather than gene amplification or mutation that contributes to disease progression in breast cancer." (PMID 30559934, 2018). "Interestingly, analysis of a small number of specimens suggests that among breast cancer subtypes, GLO1 activity is highest in TNBC." (PMID 30559934, 2018). "Interestingly, in the METABRIC dataset (n = 1904), where Glo1 was highly expressed in luminal B and basal-like breast cancers, approximately 90% (180 of 199 patients) of basal-like tumors were classified as neoplasm histologic grade 3." (PMID 30559934, 2018). "Efficient GLO1 silencing in breast cancer cells was assessed by Glo1 immunoblotting." (PMID 27759563, 2016). "Indeed, we found that the expression of YAP target genes and GLO1 showed a significant inverse correlation in breast cancer patients." (PMID 27759563, 2016). "To investigate whether triple negative breast cancer cells could respond to MG stimulation by increasing Glo-1 expression and activity, we treated breast cancer cells with MG at 300, 500 or 1000 μM during 6 hours." (PMID 24978626, 2014). "Additionally, GLO1 was more highly expressed in all breast cancer subtypes than in normal tissues." (PMID 40492378, 2025). "Besides, the role of GLO1 in mediating the invasion and metastasis of breast cancer remains unclear." (PMID 40492378, 2025). "The intricate interplay of Glo1 with molecular pathways and its dualistic role underscores the need for further research to unveil its complete biological portrait, offering novel therapeutic targets and refining treatment approaches in the relentless battle against breast cancer." (PMID 38785990, 2024).
breast carcinoma (continued). "We have confirmed this in breast carcinoma, but it could not be evidenced clinically in colorectal carcinoma, in which low Glo-1 activity was found to be associated with poor prognostic high stage tumors." (PMID 39682111, 2024). "However, a tumor-suppressing role of Glo1 has also been identified in breast cancer cells." (PMID 35898868, 2022). "This suggests GLO1 may be function in CD44-positive CSCs in luminal A breast cancers." (PMID 30559934, 2018). "It appears, therefore, that basal-like breast cancers may be highly sensitive to GLO1 inhibition." (PMID 30559934, 2018). "In the present study, we showed that high expression of Glo1 correlates with tumor grade and the occurrence of grade 3 tumors, which is consistent with earlier immunohistochemical findings indicating that overexpression of GLO1 correlated positively with tumor grade in breast cancer." (PMID 30559934, 2018). "In addition, upregulation of GLO1 mRNA was observed in breast cancer patients compared to controls." (PMID 29321821, 2017). "Furthermore, serum GLO1 enzyme activity may serve as noninvasive biomarkers for breast cancer diagnosis." (PMID 29321821, 2017). "In breast cancer cells and ATC cells, MG scavengers (e.g., carnosine, aminoguanidine) as well as GLO1 agonists (e.g., resveratrol) have been shown to reverse the invasive phenotype of cells induced by MG stress." (PMID 40352588, 2025). "In contrast, when BT549 breast cancer cells were injected into the footpads of BALB/c nude mice, LNs from the GLO1 knockdown group presented noticeably smaller volumes." (PMID 40492378, 2025). "The inhibitors of Glo1 (TLSC702) and PKCλ (aurothiomalate) emerge as potential pharmacological approaches to manage late-stage breast cancer by suppressing cell viability and tumor-sphere formation." (PMID 38785990, 2024). "Therefore, we next investigated if genes hypermethylated in their regulatory region could be enriched among anti-oncogenic pathways, which could suggest a potential inhibition of those pathways leading to the pro-oncogenic phenotype we have previously observed in GLO1-depleted breast cancer cells." (PMID 36998085, 2023). "Importantly, hypermethylated pathways under GLO1 depletion comprised several silenced genes, as assessed based on RNASeq and using RT-QPCR, most of which were known as TSGs related to the metastatic process either in breast cancer or in other cancer cell types." (PMID 36998085, 2023). "The elevated expression of GLO1 was found in basal TNBC and was shown to be essential for the survival of breast cancer stem cells." (PMID 34921655, 2022). "The present work intends to look into Glyoxalase1 (GLO1) and fructosamine-3-kinase (FN3K) activity in human breast carcinoma." (PMID 35223406, 2021). "Correlation analysis with Glo1 expression gave the following: pan cancer—PPIL1, r = 0.59 and CDC5L, r = 0.58 (p < 1 × 10−6) and TRADD, r = −0.17 (p = 5 × 10−4); and for breast cancer—PPIL1, r = 0.55; CDC5L, r = 0.26 and TRADD, r = −0.20 (p < 1 × 10−6)." (PMID 34790575, 2021). "In an attempt to unveil the mechanisms by which MG stress enhances the metastatic potential of breast cancer cells, we performed genome-wide messenger RNA (mRNA) profiling of MDA-MB-231 GLO1-depleted cells." (PMID 30674353, 2019). "It has been reported that GLO1 knockdown suppresses proliferation and promotes apoptosis in MCF7 (luminal A), T47D (luminal A), and MDA-MB 231 (claudin-low) breast cancer cells." (PMID 30559934, 2018). "We therefore examined the role of GLO1 in ALDH1-positive CSCs in MDA-MB 157 and MDA-MB 468 human basal-like breast cancer cells, where GLO1 is overexpressed as compared to MCF 10A human normal-like (non-transformed) mammary epithelial cells." (PMID 30559934, 2018). "This suggests high Glo1 expression is a factor independently predictive of overall survival in luminal A and HER2-enriched breast cancers." (PMID 30559934, 2018).
breast carcinoma (continued). "For the entire dataset of breast cancer patients in the KM Plotter database, the expression of Glo1 was increased in cancer compared with nonmalignant breast tissue." (PMID 34790575, 2021). "For chemotherapy (any), analysis had adequate statistical power for Glo1 expression and patient survival for breast cancer without classification of tumor stage, grade, type, and genotype." (PMID 34790575, 2021). "Santel and colleagues found that specific GLO1 activity in curcumin-treated JIMT-1 breast carcinoma cells was lower than in non-treated cells, decreasing dose-dependently." (PMID 32721999, 2020). "Upon DUSP5 overexpression, both GLO1-depleted cells showed a decreased migratory capacity thus functionally linking DUSP5 regulation occurring under MG stress with pro-metastatic features in breast cancer cells." (PMID 30674353, 2019). "GLO1 overexpression does not correlate with different breast cancer subtypes, neither luminal A, Luminal B, Her2+ or TNBC (2.92±0.46, 3.12±0.48, 3.1±0.53 and 3.05±0.52 respectively; P = 0.06)." (PMID 29321821, 2017). "There were non-statistically significant differences in GLO1 enzyme activity among different breast cancer subtypes (P = 0.6)." (PMID 29321821, 2017). "Hence, Glo1 overexpression correlated with aggressive clinicopathological features including lymph node metastasis, lymphovascular invasion, tumor grade and TNM stage and was an independent prognostic factor for clinical outcome of breast cancer patients." (PMID 35898868, 2022). "High Glo1 expression is a negative survival factor in chemotherapy of breast cancer where adjunct therapy with a Glo1 inhibitor may improve treatment outcomes." (PMID 35269594, 2022). "Moreover, GLO1 control of cancer stem cell expansion has been demonstrated, and recent evidence suggests a tumor-promoting role of methylglyoxal in cancer progression and EMT as observed in anaplastic thyroid, colorectal, and breast cancers." (PMID 32466621, 2020). "In addition, the Glo1 inhibitor, TLSC702, and the PKCλ inhibitor, aurothiomalate, may serve as novel pharmacological approaches to manage late−stage breast cancer through suppressing both cell viability and tumor−sphere formation in MDA−MB−157 and MDA−MB−468 human basal−like breast cancer cells." (PMID 35898868, 2022). "In our hands, GLO1 knockdown or inhibition using BBGC did not induce any significant cell apoptosis and hence conferred pro-growth and pro-metastatic advantages to breast cancer cells." (PMID 27759563, 2016). "MG treatment neither affected the level of expression nor the activity of Glo-1 in MCF-7 and SKBR3 breast cancer cells." (PMID 24978626, 2014).
Anxiety (29 papers, 2009 to 2025). Intense feelings of nervousness, tension, or panic often arise in response to interpersonal stresses. "A number of studies have reported an association between Glo1 expression and anxiety-like behavior in rodents." (PMID 34953453, 2022). "Consistent with the findings that a decrease in GLO1 expression is associated with a decrease in anxiety, several studies have reported that anxiety is reduced in MG-treated mice." (PMID 34953453, 2022). "Changes in the brain expression levels of GLO1 and Gsr produce a significant impact on anxiety-related behaviours, thus establishing the causal role of these genes." (PMID 36432007, 2022). "Taken together, these results further underscore the importance of GLO1 based on its impact on anxiety-associated behaviour through the neural circuit, which is typically associated with anxiety-like behaviours." (PMID 36432007, 2022). "Genetic and pharmacological manipulations of the GLO1 system, as well as direct administration of MG, have been associated with changes in anxiety- and depression-like behaviors, ethanol consumption, and the seizure threshold." (PMID 33478138, 2021). "Previous literature pointed to both an association between increased GLO1 expression and anxiety; and the opposite, anxiety linked to decreased GLO1 expression." (PMID 34440621, 2021). "Meanwhile, Glo1, G6pdx, Aldh2, and Dld were distinctly dysregulated in the anxiety-susceptible group." (PMID 31624233, 2019). "In the anxiety-susceptible group, Glo1, G6pdx, and Aldh2 were significantly down-regulated, while Dld was up-regulated, when compared to the control group." (PMID 31624233, 2019). "Following discovery of Glo-1 gene duplication in some strains of mice with an anxiety phenotype, a link of Glo-1 to pathologic anxiety was proposed – although the anxiety phenotype was linked to both increased and decreased Glo-1 expression." (PMID 27406712, 2016). "Further, a large and common CNV in mice including the Glyoxalase 1 (Glo1) locus has been associated with anxiety-like behavior." (PMID 26011321, 2015). "For instance, modulation of Glo-1 activity was shown to regulate anxiety-like behavior and seizure-susceptibility in mice." (PMID 25709564, 2015). "Virtually all of the studies that identified associations between Glo1 expression and anxiety-like behavior utilized only male mice, although there are isolated exceptions." (PMID 23181072, 2012). "Among the behavioral phenotypes associated with GLO1, anxiety-like behavior is the most commonly reported and widely studied." (PMID 23181072, 2012). "The effect of the Glo1 duplication on anxiety-like behavior was likely offset by numerous other alleles that collectively contributed to anxiety-like behavior in the selected lines." (PMID 23181072, 2012). "Recently, findings have linked GLO1 to numerous behavioral phenotypes, including psychiatric diseases (anxiety, depression, schizophrenia, and autism) and pain." (PMID 23181072, 2012). "In mice, several lines of evidence suggest that Glo1 expression is associated with anxiety-like behavior, depression, and neuropathic pain." (PMID 23181072, 2012). "In summary, these data show that a large CNV alters Glo1 expression and is associated with differences in anxiety-like behavior in inbred and outbred mice." (PMID 19266052, 2009). "Our data significantly inform this debate by clearly establishing the primary molecular locus that causes differential Glo1 expression among mice and by providing extensive support for a positive correlation between Glo1 expression and anxiety-like behavior." (PMID 19266052, 2009). "GLO1 has been associated with anxiety although the literature remains controversial." (PMID 34440621, 2021). "As reviewed by Distler & Palmer (2012), Glo1 is implicated in anxiety-related behavior in mice." (PMID 30110355, 2018). "Interestingly, the Glo1 CNV has previously been implicated in anxiety–like behavior in mice, suggesting a differential evolution of a behavioral trait." (PMID 24917877, 2014).
Anxiety (continued). "Similarly, we found an increase in background reads at a region around the methylglyoxal detoxifier Glo1 (glyoxalase 1), a gene that is associated with anxiety in mice." (PMID 24849289, 2014). "This experimental manipulation supported a causal role for Glo1 in anxiety-like behavior." (PMID 23181072, 2012). "Thornalley has suggested the association with anxiety-like behavior “...might reflect induction of Glo1 expression as a consequence of chronic exposure to increased methylglyoxal concentration...”." (PMID 19266052, 2009). "GLO1 expression may be associated with anxiety-like behaviour, depression, and neuropathic pain." (PMID 36432007, 2022). "Interestingly, two proteomics studies have also linked GLO1 with anxiety-like behavior." (PMID 23659354, 2013). "Contrary to these findings, STZ-treated rats and Akita mice, which are models of type I diabetes, showed high anxiety with decreased GLO1 expression and accumulation of MG-derived proteins in the brain." (PMID 34953453, 2022). "GLO1 overexpression augments anxiety-like behaviour across different genetic backgrounds and in multiple behavioural tests." (PMID 36432007, 2022). "The authors of this study proposed that the brain expression of enzymes involved in the oxidative stress pathway, glyoxalase-1 (GLO1) and glutathione reductase-1 (GSR1), are associated with anxiety-like behaviours." (PMID 36362131, 2022). "GLO1 increases anxiety levels by reducing the GABAA receptor agonist MGO, which makes GLO1 a potential target for anxiety disorders." (PMID 36432007, 2022). "In contrast, Glo1 overexpression produces the opposite effects (i.e., increased anxiety-like behavior and ethanol consumption)." (PMID 33478138, 2021). "A decline in MG, a GABAA receptor agonist, in the brain by overexpression of GLO1 was proposed to explain the link to the anxiety state." (PMID 34440621, 2021). "Taken together, these results illustrate that hesperidin activates the Nrf2/ARE pathway in diabetic rats with depression and anxiety-like behaviors, subsequently upregulating Glo-1." (PMID 32982741, 2020). "In conclusion, Glo1 seems to play a role in the regulation of anxiety-related phenotypes, however its precise effect and the influence of the respective CNV remains to be discovered." (PMID 26011321, 2015). "The Glo1 gene has been described to influence anxiety-related behavior before, as discussed in a review by Distler and Palmer." (PMID 26011321, 2015). "According to these studies GLO1 is down-regulated in the brain of two separate mouse strains selectively bred for high anxiety behavior compared to their respective low-anxiety strains, a finding contradictory to the findings in the inbred strains." (PMID 23659354, 2013). "We then functionally verified by lentivirus-mediated gene transfer (overexpression and silencing by RNAi) that two genes, glyoxalase 1 (Glo1) and glutathione reductase (Gsr) regulate anxiety in mice." (PMID 23659354, 2013). "In fact, the discrepancy among these studies was used as grounds to dispute a role for Glo1 in anxiety-like behavior." (PMID 23181072, 2012). "Local Glo1 overexpression increased anxiety-like behavior, while local Glo1 knockdown decreased anxiety-like behavior." (PMID 23181072, 2012). "Despite a controversial history, recent studies have demonstrated roles for GLO1 in behavioral phenotypes, including anxiety-like behavior and pain." (PMID 23181072, 2012). "Glyoxalase I anomalies were also reported in psychiatric diseases such as mood disorder, schizophrenia and autism, where anxiety symptoms are altered." (PMID 21248374, 2011). "Over- and under-expression of Glo1 by lentiviral vectors confirmed a positive relationship between Glo1 expression and anxiety-like behavior." (PMID 19266052, 2009). "Our findings provide a molecular basis for differential expression of Glo1 and further implicate Glo1 in anxiety-like behavior." (PMID 19266052, 2009).